CYCSP25 (CYCS pseudogene 25)
Synonyms: HC10; HCP25
Gene: Processed pseudogene on chromosome 11 (31,280,672 to 31,280,987, reverse strand). Ensembl gene ENSG00000255370.
Diseases named in the same sentence as CYCSP25 in open-access papers:
CYCSP25 is named in the same sentence as 4 diseases in open-access papers, as found by Europe PMC text mining. Sharing a sentence is not in itself a finding about the gene and the disease.
CYCSP25 shares sentences with these, for which no sentence is quoted: tumor (2 papers); breast carcinoma (1); cancer (1); melanoma (1).